IL10 (interleukin 10)
Diseases named in the same sentence as IL10 in open-access papers (continued):
Sharing a sentence is not in itself a finding about the gene and the disease.
sarcopenia (continued). "The present study investigated the relationship between the plasma pro-inflammatory factors TNF-α and IL-6 and the anti-inflammatory factors IL-4 and IL-10 in the elderly population and sarcopenia." (PMID 36160136, 2022). "Increased levels of IL-6 and TNF-α and a reduced level of IL-10 have been reported in cases of sarcopenia." (PMID 34371826, 2021). "Because age-related inflammation is linked to a reduction of interleukin (IL)-10, preserving the level of anti-inflammatory cytokine IL10 during aging should disrupt the cycle of inflammation and mitochondrial dysfunction, thereby improving sarcopenia." (PMID 30696799, 2019). "In the current study, we performed a cross-sectional analysis of serum concentrations of the inflammatory cytokine IL-6 and the anti-inflammatory cytokine IL-10, and IL-6/IL-10 ratios in the context of sarcopenia in elderly individuals." (PMID 30541467, 2018). "Following adjustment for confounding factors, the presence of sarcopenia was positively correlated with IL-6, IL-10, IL-6/IL-10 ratio and inversely correlated with BMI." (PMID 30541467, 2018). "The levels of inflammation cytokine IL-6, anti-inflammatory IL-10 and IL-6/IL-10 ratio were increased in elderly sarcopenia subjects." (PMID 30541467, 2018). "In the present study, we showed that IL-6/IL-10 ratios were higher for elderly individuals with sarcopenia compared to controls." (PMID 30541467, 2018). "In conclusion, we propose that elderly individuals with sarcopenia exhibit a compromised “inflammatory status” characterized by higher IL-6, IL-10 concentrations and IL-6/IL-10 ratios." (PMID 30541467, 2018). "Ultimately, the pro-inflammatory status is predominant whereas the anti-inflammatory cytokine IL-10 is relatively insufficient in elderly individuals with sarcopenia." (PMID 30541467, 2018). "Independent associations were observed between sarcopenia and age, BMI, physical activity, nutritional risk, VFA, IL-6 levels, IL-10 levels and IL-6/IL-10 ratios." (PMID 30541467, 2018). "In the current study, we observed significantly increased levels of IL-10 in elderly individuals with sarcopenia." (PMID 30541467, 2018). "Here, we aim to explore the relationship between sarcopenia and the inflammatory cytokine interleukin-6 (IL-6), and the anti-inflammatory cytokine interleukin-10 (IL-10) in an elderly population." (PMID 30541467, 2018). "Additionally, certain methods that increase the expression of anti-inflammatory factors, such as IL-10, can alleviate muscle atrophy and delay sarcopenia." (PMID 40677895, 2025). "IL-10, conventionally recognized as an anti-inflammatory cytokine, exerts pleiotropic effects recently related to immune system responses, but has an unclear role in sarcopenia." (PMID 38338718, 2024). "It was found that patients with sarcopenia have increased pro-inflammatory cytokine levels (interleukin-6, tumor necrosis factor α (TNFα)), C-reactive protein, and decreased levels of anti-inflammatory cytokine interleukin-10." (PMID 38505257, 2024). "Additionally, circulating levels of IL-6 and IL-10, two sarcopenia-related cytokines, were measured by ELISA." (PMID 38338718, 2024). "IL-10 and IL-6 concentrations have been seen to be increased in patients with sarcopenia, as well as the IL-6/IL-10 ratio, suggesting that the increase in IL-10 might be a compensatory mechanism elicited to suppress the effects of increased IL-6 expression." (PMID 36499366, 2022). "Patients with sarcopenia seemed to have a lower IL-10 level." (PMID 35237317, 2022). "In female patients, although the level of IL-10 in patients with sarcopenia was lower than that in patients with normal muscle index, there was no statistical difference, which may be related to the small sample size." (PMID 35237317, 2022). "After further correction of plasma IL-10 and IL-4 levels, increased plasma TNF-α level remains associated with sarcopenia, suggesting that immune aging may be involved in the pathogenesis of sarcopenia." (PMID 36160136, 2022).
sarcopenia (continued). "Additionally, interleukin 10 (IL-10), SOD1, and NOD-like receptor protein 3 (NLRP3) deficient mice have also been employed in studying the pathogenesis of sarcopenia as well as the intervention of therapeutically targeting such a disease." (PMID 35563724, 2022). "Therefore, the IL-6/IL-10 ratio is being used as a reliable marker to judge the inflammatory status, and it practically tends to increase in elderly sarcopenia patients." (PMID 35215448, 2022). "Interleukin (IL)-10 concentration in the blood is known to inhibit tumor necrosis factor (TNF)-α, and increases in cytokine levels as a result of aging are believed to be closely associated with sarcopenia." (PMID 34200794, 2021). "Thus, OLE treatment significantly reduces the IL-6/IL-10 ratio in aged rats, which has been used as a biomarker of sarcopenia in humans." (PMID 34067004, 2021). "Based on previous studies arguing for a correlation between systemic inflammation and sarcopenia, we next analyzed circulating levels of IL-10 and IL-6 as surrogates for anti- and pro-inflammatory cytokines in our cohort of patients using multiplex immunoassay." (PMID 31597337, 2019). "Because increases of IL6, TNFα, and MCP1 were reported as biomarkers and reasons for age-related inflammation and sarcopenia, IL10 could reduce these pro-inflammatory cytokines and mitigate age-related inflammation and sarcopenia." (PMID 30696799, 2019). "We observed positive associations between sarcopenia and levels of IL-6, IL-10 and IL-6/IL-10 ratios, and a negative association between sarcopenia and BMI." (PMID 30541467, 2018). "Finally, we performed multivariate analyses to assess the relationship between sarcopenia and IL-6 levels, IL-10 levels and IL-6/IL-10 ratios." (PMID 30541467, 2018). "Higher levels of IL-6 and IL-10 were observed in participants with sarcopenia (P < 0.05)." (PMID 30541467, 2018). "The increased IL-10 levels observed in elderly sarcopenia patients might therefore be compensatory, in an attempt to suppress the chronic low level inflammatory state." (PMID 30541467, 2018). "Thus, both skeletal muscle and cognitive functions are affected by chronic inflammation in vivo, and elevated levels of pro-inflammatory cytokines (IL-6 and TNF-α) and decreased levels of anti-inflammatory cytokines (IL-10) may contribute to sarcopenia and CI." (PMID 37962457, 2023). "Therefore, the present study explores the relationship between sarcopenia and IL-4, IL-6, IL-10, and TNF-α in the elderly population of agricultural and pastoral areas of Xinjiang, China, and is expected to lay a preliminary foundation for understanding its underlying mechanism." (PMID 36160136, 2022). "In line, we found a significant positive correlation between the pre-interventional PMI and IL-10 serum levels as an example of an anti-inflammatory cytokine and a trend towards a positive correlation between the PMI and IL-6, supporting the association between systemic inflammation and sarcopenia." (PMID 31597337, 2019). "Moreover, IL-10 may prove to be a promising therapeutic agent for the prevention of sarcopenia in the elderly." (PMID 30541467, 2018). "Furthermore, IL-6/IL-10 ratios were higher in subjects with sarcopenia (P < 0.05)." (PMID 30541467, 2018). "Thus, IL-10 may be a promising therapeutic candidate for preventing sarcopenia in elderly individuals." (PMID 30541467, 2018). "Moreover, higher ratios of IL-6/IL-10 were observed in the sarcopenia group (P < 0.05)." (PMID 30541467, 2018). "The concept of body fat, inflammation and balance between IL-10 and TNF-α, cellular senescence, mitochondrial dysfunction and sarcopenia needs to be further elucidated in the MCR participants and the role as a mediator for progression to dementia." (PMID 37371414, 2023). "Various cytokines involved in the pathogenesis of sarcopenia have been identified in foreign studies and include TNF-α, IL-1, IL-2, IL-4, IL-6, IL-8, and IL-10." (PMID 36160136, 2022).
sarcopenia (continued). "Our study performed a cross-sectional analysis of serum concentrations of IL-6, IL-10, IL-17A, and TNF-α in the context of sarcopenia in elderly individuals." (PMID 35237317, 2022). "This is consistent with previous findings, and it seems that increased IL-10 concentration induced by exercise continuously inhibited inflammatory factors, such as TNF-α, in older adults with sarcopenia and OA with high inflammatory markers." (PMID 34200794, 2021). "Sarcopenia subjects were older and had higher visceral fat tissue (VFA) than non-sarcopenia subjects (P < 0.05), along with higher IL-6 and IL-10 levels." (PMID 30541467, 2018). "The association of IL-10 to TNF-α ratio (aOR 0.98, 95% CI 0.97–0.99) and IL-10 (aOR 2.22, 95% CI 0.05–0.98) with MCR were independent of sarcopenia and BF%." (PMID 37371414, 2023). "Only low IL-10 and IL-10 to TNF-α ratio were significantly associated with MCR, independent of sarcopenia and body fat percentage." (PMID 37371414, 2023). "Nonetheless, elderly patients with Chronic Obstructive Pulmonary Disease diagnosed with sarcopenia presented high levels of IL-6 but not IL-10." (PMID 36499366, 2022). "People with sarcopenia have higher levels of IL-6, IL-10, and visceral adipose tissue than people without sarcopenia." (PMID 35250869, 2022). "Taken together, our data show that LPPS23 might reduce age-related inflammation by preserving the level of IL10 in aged SAMP8 mice, thereby preventing mitochondrial dysfunction and ROS production and ultimately improving sarcopenia." (PMID 30696799, 2019). "The disruption of the normal muscle physiology, as in the case of sarcopenia, has been shown to lead to abnormal myokine signaling culminating in a proinflammatory environment characterized by impaired IL-6 signaling, increased TNF-alpha production and decreased IL-1ra and IL-10 levels." (PMID 38698153, 2024). "Regarding the mixed results observed in our study, CRP, but not IL-10 and TNF-α, significantly related to low physical performance, a systematic review and meta-analysis of 17 studies with 11,249 individuals also showed that only CRP, but not TNF-α and IL-6, is associated with sarcopenia." (PMID 35525916, 2022). "Comparisons of living habits, disease status, biochemical indexes, and levels of interleukin (IL)-4, IL-6, IL-8, IL-10, and tumor necrosis factor (TNF)-α in sarcopenia and non-sarcopenia participants were made in this study." (PMID 36160136, 2022).
cerebral malaria (50 papers, 2008 to 2025). A sequestration of Plasmodium falciparum in the brain, which can cause coma and/or seizures. "Supporting the relevance and importance of the hyperinflammatory model, the balance of pro-inflammatory and regulatory cytokines, namely TNF and IL-10, and genetic variants in these genes, correlate with severity in human cerebral malaria." (PMID 38115011, 2023). "Hyperinflammatory experimental cerebral malaria (eCM) is induced by infection of mice deficient in the regulatory cytokine IL-10 (IL-10−/−) with Plasmodium chabaudi." (PMID 38115011, 2023). "IL-10 has also been reported to play a protective role in experimental cerebral malaria (ECM) caused by P. berghei ANKA." (PMID 30809232, 2019). "IL-10 has emerged as an important regulatory molecule with a protective role in experimental cerebral malaria (ECM) caused by Plasmodium in which it protects tissues by preventing excessive inflammation." (PMID 31711531, 2019). "Conversely, IL10 is thought to limit cerebral pathology in mice, and IL10 polymorphisms are associated with cerebral malaria." (PMID 25192715, 2014). "Elevated levels of IFN-γ, TNF, IL-12, IL-6, IL-1β, and IL-10 are initially protective, although excessive serum levels of these cytokines are associated with cerebral malaria pathology." (PMID 22336003, 2012). "Furthermore, IL-10 was suggested to have a protective role in experimental cerebral malaria, caused by Plasmodium berghei, as decreased IL-10 mRNA expression in spleen and brain correlated with increased susceptibility to infection." (PMID 35464430, 2022). "Injection of recombinant IL-10 protected susceptible mice from experimental cerebral malaria induced by Plasmodium berghei infection, and ablation of IL-10 resulted in higher plasma levels of pro-inflammatory cytokines and increased mortality of Plasmodium chabaudi-infected mice." (PMID 28293237, 2017). "Moreover, we have shown a tangible immunologic effect (i.e. elevated IL-10 levels) that is seen among children with the alleles of interest as compared to other children with cerebral malaria." (PMID 21447146, 2011). "We also found that murine NK cell production of IL-10 protected mice from experimental cerebral malaria." (PMID 40337867, 2025). "Our data from the experimental cerebral malaria (ECM) mouse model show that NK cells can be induced to produce IL-10, which protected mice from severe disease." (PMID 40337867, 2025). "Increasing pro-inflammatory cytokines like TNF-α and IF-γ, as well as certain interleukins like IL-6, IL-10, and IL-12, is probably a key to the etiology of cerebral malaria." (PMID 39204168, 2024). "In the case of experimental cerebral malaria, the authors found a higher mRNA expression of the pro-inflammatory cytokines IL-2, IL-6, IL-10, IL-17, IFN-γ, and TNF in the serum, hippocampus, and frontal cortex in mice infected with Plasmodium berghei." (PMID 39057789, 2024). "Another possible explanation is the reciprocal regulation between the concentration of the cytokines IFN-γ and IL-10 in Plasmodium infection, which is relevant given that IL-10 decreases the incidence of cerebral malaria and modulates the effects of IFN-γ." (PMID 37628731, 2023). "It was recently shown that dampening the function of CD8+ T cells by IL-10-producing NK cells can prevent experimental cerebral malaria." (PMID 35874786, 2022). "This is consistent with IL-10 functioning as a crucial anti-inflammatory and protective cytokine in experimental cerebral malaria." (PMID 34359826, 2021). "As the infection of CBA/Ca mice with P. berghei ANKA is the gold standard model for the investigation of cerebral malaria, we also analyzed mRNA expression levels of Tnf, Il1b, and Il10 in the brains of male and female mice treated with 17β-estradiol." (PMID 33841336, 2021).
cerebral malaria (continued). "In other studies, N-803 increased serum levels of the anti-inflammatory cytokine IL-10 in mice, and, in a mouse model of cerebral malaria, N-803 induced NK cells to secrete IL-10, which decreased CD8+ T cell activation in the brain." (PMID 34319980, 2021). "IL-15/IL-15Rα-Fc complexes (IL15C) have also been shown to expand CD8+ T cell, DN T cell and NK cell populations, and to protect mice against cerebral malaria via the induction of IL-10-producing NK cells." (PMID 32753607, 2020). "By contrast, the immune-dampening effects of NK cell IL-10 production are protective in the context of experimental cerebral malaria (ECM)." (PMID 31552035, 2019). "High levels of circulating IL-10 have been reported in patients with mild, severe and cerebral malaria." (PMID 30809232, 2019). "These factors and NK cell IL-10 secretion strongly impact immune responses dictating host survival in both systemic Lm infection and a model of cerebral malaria." (PMID 31552035, 2019). "Specifically, STAT3 signaling and NK cell IL-10 production is detrimental to host innate resistance to Lm, but promotes survival in a model of cerebral malaria." (PMID 31552035, 2019). "As astrocytes play an important role in maintaining the integrity of the BBB, including in the context of experimental cerebral malaria, we analyzed the extent of astrocyte activation in IL-10 KO mice infected with P. chabaudi." (PMID 29866139, 2018). "A useful parameter in cerebral malaria is the low ratio of anti-inflammatory cytokine IL-10 to pro-inflammatory cytokine TNF-α and low level of anti–GPI antibody in plasma." (PMID 29409517, 2018). "Survival from ECM is often associated with delayed liver stage development and was accompanied by a change in the interferon-γ and interleukin-10 levels at the critical time of cerebral malaria symptoms development." (PMID 27409081, 2016). "According to previous studies, the ratio of anti‐inflammatory (IL‐10) to inflammatory (TNF‐α) is a potentially useful parameter indicator in cerebral malaria." (PMID 27042299, 2016). "In particular, the balance of inflammatory Type I cytokines, such as interferon gamma (IFNG) and tumour necrosis factor (TNF), with Type II cytokines, e.g., interleukin 4 (IL4) and IL10, is thought to determine the lethality of cerebral malaria." (PMID 25192715, 2014). "Coculture of CD4+ T cells by IL-10+ B cells announced that IL-10+ B cells were in a position to induce CD4+T cells to produce large quantity of IL-10, which mediated the immunosuppression and protection from development of cerebral malaria." (PMID 24991577, 2014). "Meanwhile, individuals with the hHbS rs334 TT, IL10 rs3024500 AA, and IL17RD rs6780995 GA genotypes were more susceptible to severe malarial anaemia, cerebral malaria, and hyperpyrexia respectively." (PMID 24312262, 2013). "Additionally, production of the regulatory cytokine IL-10 by NK cells prevents overt pathology and death during experimental cerebral malaria." (PMID 31533835, 2019). "Some T helper 1 (Th1) cytokines (e.g., IFN-γ, lymphotoxin, and TNF) have been implicated in driving the immunopathological process leading to cerebral malaria, whereas some Th2 (e.g., IL-10, transforming growth factor (TGF)-β) cytokines appear to inhibit this process." (PMID 31262018, 2019). "IL-10 is involved in preventing the onset of experimental cerebral malaria (ECM)." (PMID 31608052, 2019). "In contrast, anti-inflammatory cytokines (produced by cells that include monocytes and Th2 cells) such as IL-10 and IL-13 have been shown to downregulate the production of proinflammatory cytokines and to reduce the incidence of experimental cerebral malaria (ECM) in mouse models." (PMID 28122790, 2017). "IL-10 levels are increased during malaria infection and this regulatory cytokine is thought to play a key role in dampening proinflammatory responses and preventing the development of severe malarial anemia and cerebral malaria." (PMID 24415936, 2014).